DDX11-AS1 (DDX11 antisense RNA 1)
Synonyms: CONCR; SCAT4
Gene: Long non-coding RNA gene on chromosome 12 (31,019,434 to 31,073,847, reverse strand). Ensembl gene ENSG00000245614.
Diseases named in the same sentence as DDX11-AS1 in open-access papers:
DDX11-AS1 is named in the same sentence as 3 diseases in open-access papers, as found by Europe PMC text mining. Sharing a sentence is not in itself a finding about the gene and the disease. The quoted sentences say what the papers report.
glioma (1 paper, 2025). A benign or malignant brain and spinal cord tumor that arises from glial cells (astrocytes, oligodendrocytes, ependymal cells). "Glioma, as the most lethal primary brain malignancy with poor prognosis, requires further elucidation on the functional role of long noncoding RNA (lncRNA) DDX11 antisense RNA 1 (DDX11-AS1) in its pathogenesis, despite its established oncogenic functions in other cancers." (PMID 41050080, 2025).
hepatocellular carcinoma (1 paper, 2022). A malignant tumor that arises from hepatocytes. "The purpose of this investigation was to examine the potential usefulness of lncRNA DDX11 antisense RNA 1 (DDX11-AS1) as a biomarker for diagnosis and prognosis in hepatocellular carcinoma (HCC)." (PMID 36072974, 2022).
cancer (3 papers, 2021 to 2025). A tumor composed of atypical neoplastic, often pleomorphic cells that invade other tissues. "LncRNA DDX11 antisense RNA 1 (DDX11-AS1) is recognized as having an imperative oncogenic role in different types of human cancer." (PMID 34866524, 2021). "DDX11 antisense RNA 1 (DDX11-AS1), which is located at human chromosome 12p11.21, has recently been recognized as a cancer-related lncRNA." (PMID 41050080, 2025).